HIF1A (hypoxia inducible factor 1 subunit alpha)
Diseases named in the same sentence as HIF1A in open-access papers (continued):
Sharing a sentence is not in itself a finding about the gene and the disease.
cancer (continued). "The interplay between SMURF2 and HIF1α represents a promising avenue for cancer therapy." (PMID 39697237, 2024). "Preclinical studies suggest that dexmedetomidine may promote cancer cell survival through the upregulation of HIF-1α, enhance metastasis via MMPs, and stimulate angiogenesis by increasing VEGF expression." (PMID 39597826, 2024). "In addition to its role in hypoxia, HIF-1α also plays a critical role in cancer progression by promoting tumorigenicity and angiogenesis." (PMID 38205087, 2024). "Hypoxia-inducible factor 1a (HIF-1a), known as the master modulator of oxygen homeostasis, functions as a key transcription factor regulating the expression of genes involved in various aspects of cellular processes and cancer biology." (PMID 38493183, 2024). "HIF-1α is a pivotal modulator in metabolic reprogramming, which occurs in hypoxic cancer cells." (PMID 39619695, 2024). "However, the mechanisms that enable cancer cells to adapt in early hypoxia, before the HIF1α-mediated transcription programme is fully established, remain poorly understood." (PMID 38485816, 2024). "Additionally, ISO is able to rewire cancer metabolism through inhibiting HIF1α signaling and glycolysis." (PMID 38339062, 2024). "HIF-1α target genes such as GLUT1 and VEGF are significantly elevated in high NQO1 expressing, indicating that HIF-1α transcriptional signaling may be activated in NQO1-positive cancers and confer a poor prognosis." (PMID 39120303, 2024). "Additionally, we found that levels of prolyl hydroxylases and HIF1A are associated with HNSCC patients’ overall survival, highlighting their role in cancer progression." (PMID 38928200, 2024). "Moreover, quercetin increases the therapeutic index of chemotherapy and radiotherapy by differentially affecting HIF-1α levels in healthy and cancer cells." (PMID 39519572, 2024). "Defects in carbohydrate metabolism pathways may also activate HIF-1α in cancer cells under normoxic conditions." (PMID 38542288, 2024). "It, therefore, implies that through the use of one path or the other, various routes or compensatory mechanisms may make cancer cells and other sick tissues insulated from HIF-1α-targeting therapy." (PMID 39099978, 2024). "Exosomes secreted from ST3G5high cancer cells (ST3G5high‐cExos) were found to contain high levels of hypoxia‐inducible factor 1‐alpha (HIF1α) and accumulated in MSs via uptake in macrophages (MΦs) owing to increased expression of sialic acid‐binding Ig‐like lectin 1 (CD169; also known as SIGLEC1)." (PMID 37716915, 2024). "Moreover, the cancer microenvironment is commonly hypoxic in solid tumors, shifting to the HIF-1α activation by inhibiting mitochondrial respiratory chains and affecting glycolysis." (PMID 38785834, 2024). "Via inducing glycolysis to increase energy production in cancer cells, HIF‐1α could prevent cancer cells from senescence and promote cancer cells proliferation." (PMID 38217303, 2024). "HIF1α, recognized as an oncogene, is central to the adaptation of cancer cells to the hostile TME." (PMID 39697237, 2024). "Notably, miR-210 has been identified as a key regulator by directly targeting HIF-1α, promoting angiogenesis and metastasis in various cancers." (PMID 38279330, 2024). "The SMURF2-mediated degradation of HIF1α could present a therapeutic avenue to disrupt cancer cells’ adaptive mechanisms, thereby mitigating treatment resistance." (PMID 39697237, 2024). "HIF-1α stimulates cancer progression by promoting cell proliferation and metabolic changes." (PMID 39766299, 2024). "These pathways include DNA Double-Strand Break Repair by Homologous Recombination (-log p = 4.06), Molecular Mechanisms of Cancer (-log p = 2.88), HIF1α Signaling (-log p = 2.84), Role of BRCA1 in DNA Damage Response (-log p = 2.59) and Wound Healing Signaling Pathway (-log p = 2.35)." (PMID 37694778, 2024).
cancer (continued). "Overexpression of HIF-1α and VEGF has been linked to poor prognosis in several cancers." (PMID 39766169, 2024). "In addition to cancer cells, HIF-1α is also expressed in macrophages and is involved in macrophage activation." (PMID 38474362, 2024). "Additionally, the targeting of HIF‐1α is considered a potential therapeutic approach in cancer treatment, as both HIF‐1α and its direct target, PD‐L1, have been linked to poor prognosis in HCC." (PMID 38935536, 2024). "Hypoxia and HIF-1α regulate cellular processes that promote cancer progression." (PMID 38766303, 2024). "Therefore, HIF-1α has been recognized to play an important role in diseases that can generate a hypoxic environment (e.g., malignancies)." (PMID 37588219, 2024). "SA is not only a metabolic intermediate but also a signal molecule that could regulate muscle remodeling in response to exercise in mammals, stabilize hypoxia inducible factor-1α (HIF-1α) by inhibiting prolyl hydroxylase and lead to cancer cell migration." (PMID 38592508, 2024). "Interestingly, a more direct form of drug resistance is identified, in which HIF-1α affects the uptake and efflux of drugs by cancer cells." (PMID 37475553, 2024). "Given that hypoxia activates HIF-1α to induce epithelial-mesenchymal transition (EMT) in cancer cells, we subsequently investigated cellular morphology and performed immunofluorescence to assess the localization of E-cadherin, in order to determine the potential involvement of Pol ι in this process." (PMID 38402183, 2024). "RAN translocate HIF1α into the cytoplasm, contributing to cancer progression in mitochondria." (PMID 38666828, 2024). "Thus, a CAR T cell was developed by fusing the CAR scaffold with the HIF-1α oxygen-sensitive subdomain to take advantage of the TME hypoxia to further infiltrate cancer effectively." (PMID 39609700, 2024). "The network suggested that curcumin may affect the HIF-1α-mediated “PD-L1 expression and PD-1 checkpoint pathway in cancer”." (PMID 38612546, 2024). "Studies in NSCLC have demonstrated that isoflurane concentrations of 1–3% enhance both cancer cell proliferation and invasion, although other studies suggest that sevoflurane may inhibit invasion by downregulating MMPs and HIF-1α." (PMID 39597826, 2024). "Preclinical studies suggest that ketamine may reduce cancer cell proliferation and migration by lowering intracellular calcium levels and inhibiting HIF-1α, p-AKT, and p-ERK expression, thereby reducing VEGF levels." (PMID 39597826, 2024). "Inhibiting glycolytic pathways: Some glycolytic enzymes upregulated by HIF-1α might be targeted to hamper cancer cell adaptation to a hypoxic environment." (PMID 39493156, 2024). "Indeed, HIF1A is known to be overexpressed in different cancer progressions and activates the transcription of genes involved in crucial aspects of cancer biology, such as angiogenesis, cell survival and proliferation, glucose metabolism, and invasion." (PMID 38360878, 2024). "In fact, carcinogenic signaling pathways, such as HIF-1α and RAS/PI3K/AKT, may cause resistance by enhancing the aerobic glycolysis of cancer cells, known as the “Warburg effect”." (PMID 38581001, 2024). "NRF2-silencing decreased HIF-1α accumulation in hypoxic cancer cells." (PMID 38674143, 2024). "HIF-1α plays a prominent role in tumorigenesis and cancer pathogenesis." (PMID 38399410, 2024). "For example, both HIF1α and HIF2α proteins have been extensively studied in cancer cells." (PMID 38509584, 2024). "HIF-1α serves as a pivotal regulatory factor in the context of LA with cancers." (PMID 38689341, 2024). "miR-6883 was transfected into cells under normoxia or hypoxia and western blot analysis revealed that miR-6883 downregulates CDK4/6 and HIF1α in CRC and BC cells, pointing to miR-6883 as a promising therapeutic to target hypoxic tumors or HIF1α-deregulated cancer cells." (PMID 38344066, 2024). "Epigenetic regulation of HIF1α signaling has been well-established in a variety of cancers." (PMID 38279330, 2024).
cancer (continued). "Also, some natural products such as berberine allow HIF-1α degradation induction and its anti-angiogenic effects in cancer cells and in endothelial cells." (PMID 38399410, 2024). "An axis focused on HIF-1α was found to be responsible for promoting cancer stemness and LR in HCC." (PMID 39300073, 2024). "In addition, the inhibition of Survivin and HIF-1α in vitro has been shown to sensitize cancer cells to cisplatin treatment by enhancing the activity of the execution caspase, caspase-3." (PMID 38730681, 2024). "Furthermore, HIF-1α promotes the Warburg effect in cancer cells and augments autophagy activity mediated by BCL2 and BNIP3." (PMID 38577616, 2024). "Such combination therapies may improve outcomes in cancers where SMURF2-mediated degradation of HIF1α is a key factor in therapeutic success." (PMID 39697237, 2024). "Another study detected that inhibition of glycolysis via regulation of the PTEN/Akt/HIF-1α signaling pathway may be one of the mechanisms whereby baicalein reverses 5-FU resistance in cancer cells under hypoxia." (PMID 39539438, 2024). "Furthermore, HDAC6 was found to associate with HIF-1α and with its transcriptional target, the VEGF receptor, thereby increasing their stability and activity in cancer cells." (PMID 38258065, 2023). "HIF1α transcriptionally regulate lncRNA HCG18 to promote cancer stemness and proliferation." (PMID 37583933, 2023). "A consequence of the many key genetic changes in cancer cells is the increased function of HIF-1α." (PMID 38052785, 2023). "We validated this phenotype in high HIF1a regions of cancer tissues of different organs of origin." (PMID 36980166, 2023). "The results showed that HIF-1a was highly expressed in cancer tissues." (PMID 37036874, 2023). "HIF-1α, an oxygen-sensing transcription factor, is known to determine glucose metabolism by oxidation or glycolysis in cancer cells, which could be considered adaptive changes to TAM circumstances." (PMID 37153758, 2023). "In order to determine whether stability of HIF-1α is regulated by p300 in our system, p300 was overexpressed in cancer cells." (PMID 37777750, 2023). "In this regard, we hypothesized that the pro-inflammatory cytokines in the interaction of highly invasive HCC cells and NK cells could influence the expression of HIF-1α in cancer cells and that lead to the immune escape of NK cells." (PMID 37501379, 2023). "HIF-1α is also a major mediator of inflammation that promotes cancer aggressiveness." (PMID 37511305, 2023). "Stabilized HIF-1α activates the glycolytic enzymes and cancer progression." (PMID 37176148, 2023). "In addition, 3-phosphoinositide-dependent kinase 1 (PDK1) is a downstream target of HIF-1α and is upregulated in many cancers." (PMID 37204526, 2023). "Moreover, the HIF-1α pathway plays a pivotal role in the modulation of hypoxia-related downstream gene expression and biological processes in cancer cells under hypoxic conditions." (PMID 36925652, 2023). "It was also found that succinate may promote cancer metastasis in non-small cell lung cancer cells through the succinate receptor SUCNR1-PI3K/Akt-HIF-1α pathway." (PMID 37525297, 2023). "Taking into account the dual, both inhibiting and promoting, role of HIF-1a and Nrf2 transcription factors in cancer pathogenesis, as well as pleiotropic and context-dependent behavior of ascorbate, further research is needed to develop the strategies of its potential clinical use." (PMID 37298254, 2023). "Besides, hypoxia-inducible factor 1 alpha (HIF1A), as a transcriptional factor of the homeostatic response of cells to hypoxia, is considered to inhibit cancer cell death by promoting lipid accumulation." (PMID 37488128, 2023). "Pro-cancer factors, e.g. hypoxia inducible factors 1α (HIF1α) and hepatocyte growth factor (HGF) or anti-cancer factors like tissue inhibitor of metalloproteinase 2 (TIMP-2) have been associated with cancer aggressiveness or metastasis in experimental models of cancer progression." (PMID 35953652, 2023).
cancer (continued). "Interestingly, a synergistic interaction of CAF-triggered growth factors with hypoxia-inducible factor (HIF-1α) was found to increase chemotherapy resistance and enhance the stemness of cancer stem cells in colorectal cancer." (PMID 37627173, 2023). "Because HIF-1α activation has also been reported to suppress mitochondrial function in cancer, we speculate that the deceased mitochondrial respiration in HIV-1–infected macrophages may be regulated by HIF-1α." (PMID 37798121, 2023). "Then, when studying how cancer cells cover their necessities of electron acceptors, experiments should ensure physiological oxygen concentrations, even the hypoxic condition that drives HIF1α and NRF2 activity in the core of solid tumours." (PMID 36769044, 2023). "In the signaling pathway diagram, we found that OS may induce cancer cell apoptosis by inhibiting the VEGFA/HIF-1α pathway." (PMID 37713894, 2023). "Interestingly, a molecular crosstalk between c-MYC and HIF-1A has been reported in cancer progression." (PMID 37624039, 2023). "Besides preventing HIF-1α degradation, HSPs have important roles in oncogenesis and malignant progression and can also be used as targets for cancer treatment." (PMID 37445908, 2023). "Specifically, HIF1A participates in adapting cancer cells to lower oxygen levels and it may be a late recurrence biomarker." (PMID 36994412, 2023). "In particular, in hypoxic microenvironment, fucoidan treatment significantly reduced cancer cell proliferation and the protein expression of HIF-1α and its target genes, such as TWIST, Snail, CAIX (carbonic anhydrase IX), and GLUT-1 (glucose transporter protein-1)." (PMID 37233501, 2023). "Several miRNAs modulate DDR in cancer cells with the involvement of mTOR and HIF1A." (PMID 36835100, 2023). "Importantly, HIF2A-induced stabilization of MYC/MAX heterodimer is much stronger than HIF1A-mediated degradation of MYC in human cancer cells, leading to MYC activation under hypoxia." (PMID 37998757, 2023). "HIF-1α overexpression has been disclosed to be related to a poor prognosis in many cancers." (PMID 37445908, 2023). "Accumulating evidence suggests that adaptations of carbohydrate and creatine metabolism, as well as other HIF-1α -independent mechanisms, may enable cancers to survive hypoxic conditions despite anti-HIF1α therapy." (PMID 37568758, 2023). "Activated HIF-1α acts as a transcription factor, driving the expression of genes involved in various processes, such as survival, proliferation, metabolism, migration, and angiogenesis, in cancer cells." (PMID 38138162, 2023). "Lysophosphatidic acid, which is a lipid growth factor and GPCR ligand, was found to stimulate aerobic glycolysis in cancer cells by inducing a pseudo-hypoxic response via upregulation of HIF1α levels; this response is involved in the transition of normal fibroblasts to a CAF phenotype." (PMID 38090580, 2023). "HIF-1α, as the most important hypoxic response factor, could regulate cancer angiogenesis as transcriptional factor via promoting its major target gene VEGF-A." (PMID 36793021, 2023). "As HIF1A encodes for a transcription factor with a large number of susceptible downstream genes, CIH-related induction of HIF1A can result in the increased expression of several other genes encoding proteins involved in cancer-related pathways." (PMID 36831404, 2023). "Selected clinical trials registered to ClinicalTrials.gov testing HIF-1α inhibitors in cancer." (PMID 36846589, 2023). "Nevertheless, regulations regarding HIF-1α with DOKD in cancer activity have yet to be elucidated." (PMID 37239383, 2023). "Therefore, to protect cancer cells from harmful ROS, HIF-1α activates PDK-1, impairs the Kreb cycle, thereby reducing NADH flux to the electron transport chain and generating ROS." (PMID 36891273, 2023).
cancer (continued). "Moreover, hypoxic cancer cell-conditioned media potentiate the metabolic shifts in adipocytes by increasing lipolysis in a HIF-1α dependent manner." (PMID 36670988, 2023). "These anti-cancer effects may be exerted by down-regulating the HIF-1α and NF-κB pathways and their downstream pathways." (PMID 37086261, 2023). "For instance, HIF1α is a direct target of miR-143-5p, which inhibits tumorigenesis, cancer proliferation, and progression by suppressing HIF1α expression at the post-transcriptional level and solute carrier family 2 member 1 (GLUT1) pathway downstream of HIF1α signaling." (PMID 37583933, 2023). "As a result, it can be suggested that HIF-1α promotes the Warburg effect in cancer cells." (PMID 38435444, 2023). "Since NO stabilizes hypoxia-inducible factor (HIF)-1α, causing up-regulation of heme biosynthesis, HCP-1 expression may be increased by stabilizing HIF-1α, which affects the efficiency of porphyrin accumulation by cancer cells." (PMID 38201494, 2023). "Furthermore, these results are consistent with those of earlier trials demonstrating an NF-κB/HIF-1α/VEGF axis in cancer cells using an in vivo angiogenesis assay." (PMID 37583906, 2023). "HIF1A is enriched in the ferroptosis, ROS, cancer, and apoptosis pathways of THCA." (PMID 36937508, 2023). "Another mechanism is based on calcitriol reducing the expression of prostaglandin E2 (PGE2) generated by cyclooxygenase-2 (COX-2); this potentially inhibits angiogenesis by decreasing the synthesis of vascular endothelial growth factor (VEGF) and impairing the HIF-1α pathway in cancer cells." (PMID 37299554, 2023). "We examined further whether CA modulates the HIF-1α/NF-κB tandem and thereby inhibits cancer cell migration." (PMID 37583906, 2023). "Although VHL-defective cancers can be targeted with clinical success by inhibiting its downstream effector HIF1a or VEGF-driven angiogenesis, we hypothesize that VHL function could be restored, at least in part, through ASO-mediated transcript modification." (PMID 37834310, 2023). "Third, HIF‐1α‐mediated upregulation of stemness genes could also confer drug resistance by the maintenance of cancer cell stemness on PDA‐modified 3D scaffold." (PMID 37424037, 2023). "Moreover, blocking of IL-6 increased NK cytotoxicity to HCC cells through the inhibited expression of STAT3 and HIF-1α in cancer cells." (PMID 37501379, 2023). "A better understanding of the roles of VBP1 in CHIP-mediated HIF-1α stability may provide further insights into their roles in human diseases including cancers and contribute to the development of drugs targeting HIF-1α signaling." (PMID 37201586, 2023). "One of the regulatory mechanisms of CD133 expression in cancer cells is HIF-1α." (PMID 37841777, 2023). "Therefore, the RPLP2/TLR4/PI3K/AKT axis provides a signalling pathway for regulating HIF-1α and subsequently promoting aerobic glycolysis and cancer cell growth." (PMID 38052785, 2023). "HIF-1α is a major transcription factor involved in the hypoxic response of cancer cells and activates hundreds of genes that play vital roles in angiogenesis, proliferation, glucose metabolism, invasion, and metastasis, and in resistance to radiation and chemotherapy in HCC." (PMID 37047482, 2023). "Several HIF-1α inhibitors have been tested in clinical trials of various types of cancers." (PMID 37615898, 2023). "Mint3 inhibition effectively disrupts HIF-1α-mediated inflammations or cancer progressions." (PMID 36831085, 2023). "HIF-1α is an important modulator of hypoxic response in cancer cells." (PMID 37807067, 2023). "In lung cancer, HIF-1α activates ATAD2 to enhance cancer development, which may further facilitate mitochondrial ROS production that contributes to enhancing cancer cell stemness." (PMID 36632213, 2023).